HIF1A (hypoxia inducible factor 1 subunit alpha)
Diseases named in the same sentence as HIF1A in open-access papers (continued):
Sharing a sentence is not in itself a finding about the gene and the disease.
autoimmune disease (continued). "Nevertheless, available evidence showed that HIF-1α regulates inflammatory cytokines secretion, leading to imbalance of Th1, Th2, Th17, Treg cells, and CD8+ T cells that are participating in autoimmune disorders." (PMID 36761171, 2022). "IL-38, a novel cytokine of IL-1F, is expressed in SLE, RA, psoriasis, IBD, and other autoimmune diseases with different expression levels of IL-38 via different signaling pathways, such as SIRT1/HIF-1α signaling pathways." (PMID 34539413, 2021). "HIF-1α and HIF-2α are known for their prominent roles in autoimmune diseases, immunity and cancer, and reagents to modulate their expression are being examined in clinical trials or are being developed." (PMID 33024109, 2020). "In the present study, HIF-1α was increased in CD8+ T cells of vitiligo lesions and PBMCs, which is consistent with the results of typical autoimmune diseases." (PMID 31885781, 2019). "Thus, hypoxic conditions that increase the synthesis of the HIF-1α protein, a negative regulator of FOXP3 (a bona fide marker of Treg cell) expression, significantly reduce the development and activity of Treg cells, thereby increasing the risk of inflammatory and autoimmune diseases." (PMID 29598831, 2018). "The up-regulation or down-regulation expression level of IL-38 may affect different types of autoimmune diseases via different signaling pathways, for instance, SIRT1/HIF-1α signaling pathway." (PMID 34539413, 2021). "Secondly, since HIF-1α is closely related to cell metabolism and energy supply, the relationship between HIF-1α and non-immune cells involved in the process of autoimmune diseases should be paid attention like cancer cells, renal tubular epithelial cells, and synovial cells." (PMID 36761171, 2022).
chondrosarcoma (30 papers, 2010 to 2025). A malignant cartilaginous matrix-producing mesenchymal neoplasm arising from the bone and soft tissue. "Patient-derived high-grade chondrosarcoma samples demonstrated increased HIF-1α expression levels associated with the upregulation of Bcl-xL." (PMID 38534356, 2024). "In this study, we sought to determine the potential association of IDH mutation and HIF-1α in chondrosarcoma." (PMID 35198082, 2022). "Consistently, in our study, RNA-Seq data analysis of chondrosarcoma JJ012 cells revealed downregulation of several HIF-1α target genes upon loss of IDH1mut." (PMID 35198082, 2022). "As an example, increased expression of HIF1α and HIF2α in chondrosarcomas is associated with worse patient survival." (PMID 24216979, 2013). "In addition, mutations found in chondrosarcoma such as mutations located in IDH1/2 (>50% of chondrosarcomas) have been described to induce constitutive activation of HIF-1α and Hif-2α factors." (PMID 37046623, 2023). "In this study, we sought to determine the association of IDH mutation and HIF-1α in chondrosarcoma." (PMID 35198082, 2022). "HIF-1α-induced VEGF expression is implicated in the angiogenic switch in chondrosarcoma." (PMID 35198082, 2022). "Moreover, high HIF-1α expression has been linked to shorter disease free and overall survival in chondrosarcoma patients." (PMID 29361725, 2018). "HIF1α and HIF2α up-regulation play a prominent role in evasion of apoptosis and tumor progression associated with high Bcl-xL and low Beclin 1 expression in chondrosarcomas." (PMID 24216979, 2013). "Thus, we endeavored to determine whether HIF-1α contributes to the oncogenic properties of IDH mutation in the JJ012 chondrosarcoma cells." (PMID 35198082, 2022). "To determine whether HIF-1α is a contributor in IDH mutation-driven tumorigenesis of chondrosarcoma, we examined the capacity of JJ012 parental and IDH1mut KO cells for anchorage-independent growth under normoxia and hypoxia conditions in a soft-agar colony formation assay." (PMID 35198082, 2022). "Since anchorage-independent growth is tightly correlated with tumorigenic potential in vivo, it is conceivable that the attenuated HIF-1α signaling caused by loss of IDH1mut might contribute to the observed inhibition of chondrosarcoma formation in the xenograft model." (PMID 35198082, 2022). "Isocitrate dehydrogenase 1 mutations were reported to induce HIF-1α and consequently influence angiogenic properties and tumorigenicity in the JJ012 human chondrosarcoma cell line." (PMID 38534356, 2024). "In malignant chondrosarcoma, HIF-1α activates VEGF-A expression, a cytokine that plays a crucial role in neoangiogenic process, but also CXCR4 and MMP1, which mediate cell migration and invasion, as a response to the hypoxic microenvironment." (PMID 35893766, 2022). "In another study, a high expression of HIF-1α was observed in patients with chondrosarcomas, and the increased expressions of HIF-1α were correlated with higher histological grades and clinical outcomes." (PMID 35163019, 2022). "In another study, the mTOR inhibitor everolimus suppressed the expressions of Glut1 and HIF1α, cell proliferation, and prevented tumor progression in a rat orthotopic chondrosarcoma model." (PMID 35163019, 2022). "In conclusion, mounting evidence is emerging that HIF-1α strongly correlates with the grade and prognosis of chondrosarcoma." (PMID 35893766, 2022). "Nonetheless, herein, we identified a strong correlation between HIF-1α activation and IDH1 mutation status in chondrosarcoma cells." (PMID 35198082, 2022). "A 2011 study identified that HIF-1α as well as Bcl-xL expression was significantly higher in chondrosarcomas when compared to benign cartilaginous tumors and conferred a significantly worse overall survival." (PMID 34067530, 2021).
chondrosarcoma (continued). "Although we identified a specific association between HIF-2α expression and several aspects of chondrosarcoma malignancy, there has been a general notion of redundancy between HIF-1α and HIF-2α as a common downstream effector of hypoxia." (PMID 33024108, 2020). "In recent studies, researchers have found that PI3K/AKT/mTOR and HIF-1α pathway has been involved in the VEGF-A-dependent angiogenesis in human chondrosarcoma induced by adiponectin." (PMID 26958938, 2016). "Instead, we employed SW1353 chondrosarcoma cells for the application of siRNA against HIF1α because of their relatively high physiological HIF1α protein expression." (PMID 26273614, 2015). "MTOR inhibitor everolimus blocks cell proliferation, Glut1 expression and HIF1a expression, and prevents in vivo chondrosarcoma tumor progression in both macroscopic and in adjuvant phase post R1 resection." (PMID 22761648, 2012). "Another study concluded that in chondrosarcoma, HIF-1α expression was only present in 40% of tumors sampled; however, this study was unique in staining for nuclear HIF-1α, the active form." (PMID 21234363, 2011). "This study provides the first indication that CXCR4 is regulated by hypoxia and specifically HIF-1a in chondrosarcoma cells." (PMID 20102637, 2010). "Concerning chondrosarcoma, HIF-1α stabilization is observed when cells are cultured in hypoxia." (PMID 37046623, 2023). "Given the apparent association of HIF-1α expression with IDH1 mutation, we asked whether such mutation confers angiogenic properties on the chondrosarcoma JJ012 cells." (PMID 35198082, 2022). "Interestingly, it has been reported that glucose metabolism and hypoxia-inducible factor (HIF1a) levels are elevated in chondrosarcomas and correlated with a higher pathological grade and lower patient survival rate." (PMID 33762012, 2021). "Inhibition of mTOR in chondrosarcoma cell lines and animal models has led to anti-tumor responses via reduction of glycolysis, oxidative metabolism, cellular proliferation, and Glut1 and HIF-1α expression." (PMID 34067530, 2021). "In chondrosarcoma, HIF-1α could promote the expression of vascular endothelial growth factor (VEGF), which was the primary cytokine related to angiogenesis." (PMID 30782196, 2019). "Furthermore, increased expression levels of HIF-1α played a prominent role in evasion of apoptosis and chondrosarcoma progression through upregulation of Bcl-xl." (PMID 30782196, 2019). "We further explored whether PI3K, Akt, and mTOR signals were involved in adiponectin-induced HIF-1α activation in human chondrosarcoma cells." (PMID 26468982, 2015). "HIF1α is a key element in tumor hypoxia and is overexpressed in chondrosarcoma." (PMID 22761648, 2012). "The hypoxia mediated increase in MMP1 expression and chondrosarcoma invasion could be inhibited by siRNA directed at HIF-1a or CXCR4, the CXCR4 inhibitor AMD3100, as well as with ERK inhibitor U0126 and ERK siRNA." (PMID 20102637, 2010). "Our results show that HIF-1a also upregulates CXCR4 in chondrosarcoma." (PMID 20102637, 2010). "The survival rate of patients was reciprocal with HIF-1α positivity, suggesting prognostic roles of HIF-1α in chondrosarcoma." (PMID 38534356, 2024). "In our current investigation, we discovered that visfatin stimulates the Raf/MEK/ERK pathway and activates HIF-1α as well as suppresses the expression of miR-2277-3p, thereby promoting VEGF-D-mediated lymphangiogenesis in chondrosarcoma." (PMID 38791180, 2024). "Visfatin stimulation increased HIF-1α expression, which was inhibited by GW5074, PD98059, and U0126, indicating that visfatin enhances VEGF-D expression in human chondrosarcoma cells by activating the RAF, MEK, ERK, and HIF-1α pathways." (PMID 38791180, 2024). "In this report, we stimulated the HIF-1α-dependent hypoxic response in chondrosarcoma cells using dimethyloxalylglycine (DMOG), a chemical compound that stabilizes HIF-1α." (PMID 35893766, 2022).
chondrosarcoma (continued). "We then examined the relationship between the presence of HIF1A or EPAS1 gene amplification and the occurrence of dedifferentiation, recurrence, or metastasis in chondrosarcoma patients." (PMID 33024108, 2020). "In chondrosarcoma cell lines, r-adiponectin promoted VEGF-A expression via ADIPOR activating the PI3K-AKT-mTOR pathway and HIF-1α." (PMID 29361725, 2018). "This is likely the result of the elevated HIF-1α, observed in chondrosarcoma biopsies, and is required for hypoxia-induced VEGF expression in chondrosarcoma cell lines." (PMID 29098360, 2018). "Here we found that adiponectin induced VEGF-A expression and subsequently promoted angiogenesis and tumor growth in human chondrosarcoma cells through the activation of AdipoR1/R2 receptor, PI3K, Akt, mTOR, and HIF-1α signaling pathways." (PMID 26468982, 2015). "Using transient transfection with HRE-luciferase as an indicator of HIF-1α activity, we found that adiponectin also dramatically increased HRE-luciferase activity in chondrosarcoma cells." (PMID 26468982, 2015). "Here we reported that adiponectin promotes VEGF-A expression in human chondrosarcoma via activation of phosphoinositide 3 kinase (PI3K), Akt, mammalian target of rapamycin (mTOR), and hypoxia-inducible factor-1α (HIF)-1α signaling pathways." (PMID 26468982, 2015). "These suggest that AdipoR/PI3K/Akt/mTOR/HIF-1α is a common pathway responsible for VEGF-A expression and angiogenesis in chondrosarcoma cells." (PMID 26468982, 2015). "siRNA directed against HIF-1a, CXCR4, ERK; CXCR4 blockade with AMD3100; or ERK inhibitor U0126 all efficiently inhibited the increase in invasion of chondrosarcoma cells during hypoxia." (PMID 20102637, 2010). "Chondrosarcoma cell invasion is increased by hypoxia induced expression of CXCR4 and MMP1 and is mediated by HIF-1a and ERK." (PMID 20102637, 2010). "Hypoxia and specifically HIF-1a increased CXCR4 and MMP1 expression in JJ cell line and chondrosarcoma invasion in vitro." (PMID 20102637, 2010). "The present study determined the effect of hypoxia and specifically HIF-1a on expression of CXCR4 and MMP1 and their role in chondrosarcoma cell invasion." (PMID 20102637, 2010). "Expression of both HIF-1α and HIF-2α has been reported in chondrosarcoma and giant cell tumour of bone, HIF-1α expression correlating with reduced disease-free survival in chondrosarcoma." (PMID 20637078, 2010). "Angiogenesis is promoted by VEGF, but HIF-1α is not the only factor that stimulates VEGF expression in chondrosarcomas." (PMID 38534356, 2024). "Interestingly, two studies evaluated the expression of HIF-1α in cartilage tumors and suggested that HIF-1α expression was significantly correlated with shorter disease-free survival in chondrosarcoma." (PMID 35198082, 2022). "Thus, we treated SW 1353 chondrosarcoma cells with DMOG, a compound that stabilizes HIF-1α, thereby mimicking hypoxia, and performed a quantitative secretome analysis to identify proteins that were differentially released in response to hypoxia." (PMID 35893766, 2022). "Similarly, the mTOR pathway was studied in a preclinical rat chondrosarcoma model by utilizing the mTOR inhibitor everolimus which blocked cell proliferation as well as GLUT1 and HIF1a expression in vivo." (PMID 34938658, 2021). "Although we did not demonstrate the mechanism of exogenous ADPN on angiogenesis during ischemia, it is possibly related to the HIF-1α/VEGF signaling, as it was reported that ADPN could promote angiogenesis via VEGF in human chondrosarcoma." (PMID 34336097, 2021). "VEGF, FGF2, endothelin-1 (ET-1) and hypoxia-inducible factor-1α (HIF-1α) expression and mitogen activated protein kinase (MAPK) signaling are significantly enhanced in G2 and G3 conventional chondrosarcomas compared to G1 chondrosarcomas." (PMID 29361725, 2018).
chondrosarcoma (continued). "Immunostaining and siRNA experiments have been used to demonstrate that chondrosarcoma tumors of all grades express HIF-1α at higher levels than do normal chondrocytes and benign cartilaginous tumors, and that VEGF expression is dependent on HIF-1α." (PMID 21234363, 2011). "Several authors demonstrated that malignant chondrocytes increased HIF-1α expression in an oxygen concentration-dependent manner and increased V-EGF expression in response to hypoxia which is closely related to the potential malignancy of chondrosarcoma." (PMID 21647363, 2011). "Interestingly, chondrosarcoma cell invasion is increased by hypoxia-induced expression of CXCR4 and MMP1, a process mediated by HIF1α and ERK, and CXCL12, also called SDF-1, increases the invasiveness of chondrosarcoma cells." (PMID 21647363, 2011). "However, this project is the first to link the combined effects of HIF-1a on CXCR4 and MMP1 expression and the indirect effect of HIF-1a on MMP1 expression acting through CXCR4, which independently increases MMP1 in chondrosarcoma cells." (PMID 20102637, 2010). "Moreover, the GO analysis with Molecular Function and Cellular Component annotations also supported non-redundant, and distinct features of HIF-2α in chondrosarcoma cells compared to that of HIF-1α." (PMID 33024108, 2020). "Finally, we investigated whether potential associations exist between gene amplification at the loci of HIF family genes, HIF1A or EPAS1, and various aspects of chondrosarcoma malignancy, including patient prognosis." (PMID 33024108, 2020). "Therefore, integrin and HIF-1α signaling might intertwine with each other by shared mediators such as angiogenic factors in the tumor microenvironment, and thus both pathways contribute to the process of angiogenesis in IDH-mutant chondrosarcomas." (PMID 35198082, 2022). "Ewing sarcoma cells but not chondrosarcoma cells showed a metabolic profile consistent with aerobic glycolysis, i.e. increased glucose uptake, LDH activity, lactate production and HIF-1α activation." (PMID 26252771, 2015). "Interestingly, only 31 were commonly regulated by both HIFs, thus suggesting a high degree of non-redundancy for HIF-1α and HIF-2α in regard to target gene specificity in chondrosarcoma cells." (PMID 33024108, 2020).
inflammatory bowel disease (30 papers, 2012 to 2026). A spectrum of small and large bowel inflammatory diseases of unknown etiology. "Collectively, these findings highlight the critical importance of HIF-1α in IgA class switching and the potential for targeting the HIF-1α-dependent metabolic‒epigenetic axis to treat inflammatory bowel diseases and other inflammatory disorders." (PMID 39543372, 2025). "Previous studies have shown that the modulation of the HIF-1α pathway can reduce inflammatory responses in mouse models of inflammatory bowel disease." (PMID 40110637, 2025). "HIF-1α protects the intestinal barrier in inflammatory bowel diseases and ameliorates mucosal damage." (PMID 37840730, 2023). "HIF-1α was reported to increase CD11b expression in B-cells, which act as suppressors in inflammatory bowel disease." (PMID 35242132, 2022). "Our study further verified the therapeutic mechanism of HIF-1α stabilizer in patients with inflammatory bowel disease." (PMID 35711312, 2022). "Studies have shown that the activation of HIF-1α contributes to the progression of inflammatory bowel disease, while the inhibition of HIF-1α activity helps to alleviate intestinal inflammation." (PMID 36164339, 2022). "HIF-1α is a common transcription factor induced by ADORA2B activation in inflammatory bowel disease and urologic diseases." (PMID 26228921, 2015). "Furthermore, NF-κB is one of the most recognized transcription factors regulating HIF-1α in the inflammatory microenvironment such as in inflammatory bowel disease." (PMID 27548209, 2016). "Moreover, HIF-1α stabilization in conditions such as inflammatory bowel disease, pathogen infection, acute lung injury and organ transplantation has been associated with beneficial results." (PMID 25744540, 2015). "HIF (hypoxia-inducible factor) can affect inflammatory bowel disease (IBD) through multiple mechanisms under hypoxic conditions: When hypoxia occurs, the stability of HIF-1α/2α is enhanced and downstream genes are activated." (PMID 40771912, 2025). "The benefits of HIF-1α stabilizer on inflammatory bowel disease (IBD) also still need further studies (NCT04556383)." (PMID 36724056, 2023). "Here, we analyzed the potential role of gut bacteria and the hypoxia-inducible factor 1α (HIF1α) pathway in regulating mucosal IL18 expression in inflammatory bowel disease (IBD)." (PMID 38163085, 2023). "Additional investigations in the context of chronic inflammation like inflammatory bowel disease (IBD) have shown that hypoxia and HIF-1α impair UCB-induced CD39 upregulation in Th17 cells that become less responsive to AhR activation." (PMID 33553158, 2020). "Colonic tissues in Inflammatory Bowel Disease (IBD) patients exhibit oxygen deprivation and activation of hypoxia-inducible factor 1α and 2α (HIF-1α and HIF-2α), which mediate cellular adaptation to hypoxic stress." (PMID 30455703, 2018). "In inflammatory bowel disease (IBD), mucosal CD71 expression rises on both basolateral and apical enterocyte membranes and is shaped by inflammation-driven HIF-1α signaling, which in turn can induce CD71 and alter iron handling." (PMID 41375568, 2025). "We have also assessed HIF-1α, p38-MAPK and CD36 immunostaining in the mucosa of patients with inflammatory bowel disease." (PMID 23119050, 2012). "Immunohistochemical studies revealed CD36, HIF-1α and p38-MAPK expression in the mucosa of patients with inflammatory bowel disease." (PMID 23119050, 2012).